CDK1 (cyclin dependent kinase 1)
Description:
Plays a key role in the control of the eukaryotic cell cycle by modulating the centrosome cycle as well as mitotic onset; promotes G2-M transition via association with multiple interphase cyclins. CDK1/CDC2-cyclin-B controls pronuclear union in interphase fertilized eggs. Essential for early stages of embryonic development. During G2 and early mitosis, CDC25A/B/C-mediated dephosphorylation activates CDK1/cyclin complexes which phosphorylate several substrates that trigger at least centrosome separation, Golgi dynamics, nuclear envelope breakdown and chromosome condensation. Once chromosomes are condensed and aligned at the metaphase plate, CDK1 activity is switched off by WEE1- and PKMYT1-mediated phosphorylation to allow sister chromatid separation, chromosome decondensation, reformation of the nuclear envelope and cytokinesis. Phosphorylates KRT5 during prometaphase and metaphase (By similarity). Activated by the CDK-activating kinase (CAK) complex consisting of CDK7, cyclin-H/CCNH and MAT1, which is a master regulator of CDK activity. Inactivated by PKR/EIF2AK2- and WEE1-mediated phosphorylation upon DNA damage to stop cell cycle and genome replication at the G2 checkpoint thus facilitating DNA repair. Reactivated after successful DNA repair through WIP1-dependent signaling leading to CDC25A/B/C-mediated dephosphorylation and restoring cell cycle progression. Catalyzes lamin (LMNA, LMNB1 and LMNB2) phosphorylation at the onset of mitosis, promoting nuclear envelope breakdown. In proliferating cells, CDK1-mediated FOXO1 phosphorylation at the G2-M phase represses FOXO1 interaction with 14-3-3 proteins and thereby promotes FOXO1 nuclear accumulation and transcription factor activity, leading to cell death of postmitotic neurons. The phosphorylation of beta-tubulins regulates microtubule dynamics during mitosis. NEDD1 phosphorylation promotes PLK1-mediated NEDD1 phosphorylation and subsequent targeting of the gamma-tubulin ring complex (gTuRC) to the centrosome, an important step for spindle formation. In addition, CC2D1A phosphorylation regulates CC2D1A spindle pole localization and association with SCC1/RAD21 and centriole cohesion during mitosis. The phosphorylation of Bcl-xL/BCL2L1 after prolongated G2 arrest upon DNA damage triggers apoptosis. In contrast, CASP8 phosphorylation during mitosis prevents its activation by proteolysis and subsequent apoptosis. This phosphorylation occurs in cancer cell lines, as well as in primary breast tissues and lymphocytes. EZH2 phosphorylation promotes H3K27me3 maintenance and epigenetic gene silencing. CALD1 phosphorylation promotes Schwann cell migration during peripheral nerve regeneration (By similarity). CDK1-cyclin-B complex phosphorylates NCKAP5L and mediates its dissociation from centrosomes during mitosis. Regulates the amplitude of the cyclic expression of the core clock gene BMAL1 by phosphorylating its transcriptional repressor NR1D1, and this phosphorylation is necessary for SCF(FBXW7)- mediated ubiquitination and proteasomal degradation of NR1D1. Phosphorylates EML3 at 'Thr-881' which is essential for its interaction with HAUS augmin-like complex and TUBG1. Phosphorylates CGAS during mitosis, leading to its inhibition, thereby preventing CGAS activation by self DNA during mitosis. Phosphorylates SKA3 on multiple sites during mitosis which promotes SKA3 binding to the NDC80 complex and anchoring of the SKA complex to kinetochores, to enable stable attachment of mitotic spindle microtubules to kinetochores. (Microbial infection) Acts as a receptor for hepatitis C virus (HCV) in hepatocytes and facilitates its cell entry.
Synonyms: CDC2; CDC28A; P34CDC2
Tractability: Small molecule: a drug acting on it is in phase 2 or 3 trials; a structure with a bound ligand is known; a high-quality ligand is known; it belongs to a druggable protein family. PROTAC: it is named in the literature on targeted protein degradation; UniProt records ubiquitination sites on it; ubiquitination databases record sites on it; its protein half-life has been measured; a small molecule that binds it is known.
Target class: CMGC protein kinase CDC2 subfamily; Kinase; CMGC protein kinase CDK family; CMGC protein kinase group; Enzyme; Protein Kinase
Chemical probes: BMS-265246, PD080789, PD080991, PD081175, PD081438, PD081572, PD082009, PD082662, PD082849, PD082953, PD083478, PD083934, PD084487, PD084706, PD085321, TMX-2172 (high quality)
Safety:
Unwanted effects reported when the protein is acted on. In parentheses: how it was acted on, where the effect was seen, and who reports it.
pneumonitis (source: ClinPGx)
Gene: Protein-coding gene on chromosome 10 (60,778,312 to 60,796,236, forward strand). Ensembl gene ENSG00000170312.
Subcellular location: Nucleus; Cytoplasm; Mitochondrion; Cytoplasm, cytoskeleton, microtubule organizing center, centrosome; Cytoplasm, cytoskeleton, spindle
Subcellular location (Human Protein Atlas): Cytosol; Nucleoplasm; Acrosome; Connecting piece; Flagellar centriole; Perinuclear theca
Pathways (Reactome):
Cell Cycle: APC/C:Cdc20 mediated degradation of Cyclin B; AURKA Activation by TPX2; Activation of NIMA Kinases NEK9, NEK6, NEK7; Cdc20:Phospho-APC/C mediated degradation of Cyclin A; Chk1/Chk2(Cds1) mediated inactivation of Cyclin B:Cdk1 complex; Condensation of Prometaphase Chromosomes; Condensation of Prophase Chromosomes; Cyclin A/B1/B2 associated events during G2/M transition; Depolymerization of the Nuclear Lamina; E2F-enabled inhibition of pre-replication complex formation; G1/S-Specific Transcription; G2/M DNA replication checkpoint; Golgi Cisternae Pericentriolar Stack Reorganization; Initiation of Nuclear Envelope (NE) Reformation; Loss of Nlp from mitotic centrosomes; Loss of proteins required for interphase microtubule organization from the centrosome; MASTL Facilitates Mitotic Progression; Mitotic Prophase; Nuclear Pore Complex (NPC) Disassembly; Phosphorylation of Emi1; Phosphorylation of the APC/C; Recruitment of NuMA to mitotic centrosomes; Recruitment of mitotic centrosome proteins and complexes; Regulation of APC/C activators between G1/S and early anaphase; Regulation of PLK1 Activity at G2/M Transition; Resolution of Sister Chromatid Cohesion; The role of GTSE1 in G2/M progression after G2 checkpoint; Transcription of E2F targets under negative control by p107 (RBL1) and p130 (RBL2) in complex with HDAC1
Gene expression (Transcription): Transcriptional regulation by RUNX2
Signal Transduction: MAPK3 (ERK1) activation; MAPK6/MAPK4 signaling
Immune System: PKR-mediated signaling
Metabolism of proteins: Ovarian tumor domain proteases
Organelle biogenesis and maintenance: Anchoring of the basal body to the plasma membrane
Gene Ontology:
Molecular function: cyclin binding; cyclin-dependent protein kinase activity; cyclin-dependent protein serine/threonine kinase activity; histone kinase activity; kinase activity; protein binding; protein kinase activity; protein serine kinase activity; protein serine/threonine kinase activity; RNA polymerase II CTD heptapeptide repeat kinase activity; ATP binding; chromatin binding; Hsp70 protein binding
Biological process: DNA damage response; epithelial cell differentiation; G1/S transition of mitotic cell cycle; G2/M transition of mitotic cell cycle; microtubule cytoskeleton organization involved in mitosis; mitotic nuclear membrane disassembly; negative regulation of apoptotic process; negative regulation of protein ubiquitination; peptidyl-threonine phosphorylation; positive regulation of G2/M transition of mitotic cell cycle; positive regulation of mitochondrial ATP synthesis coupled electron transport; positive regulation of mitotic sister chromatid segregation; positive regulation of protein localization to nucleus; positive regulation of smoothened signaling pathway; positive regulation of ubiquitin-dependent protein catabolic process; protein localization to kinetochore; regulation of attachment of mitotic spindle microtubules to kinetochore; regulation of circadian rhythm; regulation of heterochromatin organization; cell migration; centrosome cycle; DNA repair; DNA replication; ERK1 and ERK2 cascade; Golgi disassembly; and 24 more
Cellular component: centrosome; chromosome, telomeric region; cyclin B1-CDK1 complex; cyclin-dependent protein kinase holoenzyme complex; cytoplasm; cytosol; extracellular exosome; membrane; midbody; mitochondrial matrix; mitotic spindle; nucleoplasm; nucleus; spindle microtubule; cyclin A1-CDK1 complex; cyclin A2-CDK1 complex; endoplasmic reticulum membrane; mitochondrion; spindle
Genetic constraint (gnomAD): Loss-of-function variants: 1 observed, 8.4 expected, observed/expected ratio (o/e) 0.12, 90% interval 0.041 to 0.56. That is too few expected variants to judge how well the gene tolerates losing a copy. Missense variants: 51 observed, 117.09 expected, observed/expected ratio (o/e) 0.44, 90% interval 0.35 to 0.55. Synonymous variants: 39 observed, 42.7 expected, observed/expected ratio (o/e) 0.91, 90% interval 0.71 to 1.19.
Homologues: Orthologues: chimpanzee CDK1 (100% identical), dog CDK1 (99% identical), macaque CDK1 (99% identical), rabbit CDK1 (99% identical), rat Cdk1 (98% identical), mouse Cdk1 (97% identical), pig CDK1 (94% identical), tropical clawed frog cdk1 (89% identical), zebrafish cdk1 (84% identical), guinea pig Cdk1 (80% identical), Drosophila melanogaster Cdk1 (72% identical), Caenorhabditis elegans cdk-1 (65% identical). Paralogues in human: CDK2 (65% identical), CDK3 (65% identical), CDK5 (56% identical), CDK17 (54% identical), CDK16 (52% identical), CDK18 (51% identical), CDK14 (50% identical), CDK15 (46% identical), CDK7 (46% identical), CDK11B (45% identical), CDK6 (45% identical), CDK11A (45% identical), and 14 more.
Diseases named in the same sentence as CDK1 in open-access papers:
CDK1 is named in the same sentence as 304 diseases in open-access papers, as found by Europe PMC text mining. Sharing a sentence is not in itself a finding about the gene and the disease. The quoted sentences say what the papers report.
breast cancer (279 papers, 2009 to 2026). A primary or metastatic malignant neoplasm involving the breast. "In fact, recent advances in genomics have facilitated the identification of important molecular markers implicated in breast cancer progression, among which CDK1 has emerged as a rising star." (PMID 41278293, 2025). "In contrast, PKMYT1 displays a distinct substrate specificity towards CDK1 and is associated with enhanced metastatic potential and diminished overall survival in colorectal and breast cancers, highlighting its role as a potential prognostic biomarker." (PMID 40664640, 2025). "We also investigated the expression levels of CDK1 in different breast cancer subgroups and its diagnostic efficacy." (PMID 41278293, 2025). "Overall survival analysis of NUSAP1, MELK, and CDK1 in breast cancer patients has provided valuable insights into the underlying mechanisms of tumor progression." (PMID 38084295, 2023). "CDK1, a cell cycle regulator, has also been implicated in breast cancer progression and is associated with decreased overall survival." (PMID 38084295, 2023). "It was reported that the high expression of CDK1 was significantly associated with a poor prognosis in breast cancer, which is consistent with our findings." (PMID 36813923, 2023). "Studies have shown that CDK1 is overexpressed in breast cancer and liver cancer, causing tumor cell proliferation and development." (PMID 36247089, 2022). "Although this RNA binding protein is regarded as an N6-methyladenosine-associated regulatory protein, its oncogenic roles in breast cancer are exerted through regulation of CDK1 in an independent manner from its association with N6-methyladenosine." (PMID 36266723, 2022). "It has been demonstrated that depletion of CDK1 or pharmacological inhibition of CDK1 increases the susceptibility of BRCA-positive breast cancer to PARP inhibitors." (PMID 35408915, 2022). "In breast cancer, up-regulation of CDK1 has been associated with short overall, relapse-free and progression-free survival times as well as advanced clinical stage." (PMID 36266723, 2022). "As an essential regulator for the cell cycle, the activity of CDK1 has long been considered a potential target, which is associated with cell cycle dysfunction and corresponding distinct molecular profiles of breast cancer." (PMID 34124255, 2021). "Studies showed overexpression of CDK1 in breast cancer, and loss of expression of CDK inhibitory proteins (CKI) by mutational or epigenetic modifications, in melanoma, lung, and breast cancers." (PMID 34769385, 2021). "The results show that combining high immunoexpressions for Securin, Separase and Cdk1 comprises a promising prognostic model indicating 8.4-fold increased risk of breast cancer death (p < 0.0001)." (PMID 32546141, 2020). "The designed model comprising immunoexpressions of Securin, Separase and Cdk1 identified 8.4-fold increased risk of breast cancer mortality (p < 0.0001)." (PMID 32546141, 2020). "Up-regulation of CDK1 is associated with poor prognosis in breast cancer and epithelial ovarian cancer." (PMID 30765611, 2019). "Loss of CEP55 sensitizes breast cancer cells to anti‐mitotic agents through premature CDK1/cyclin B activation and CDK1 caspase‐dependent mitotic cell death." (PMID 30108112, 2018). "Increased CDK1 activity reportedly predicts RCC recurrence, and an association has been found between CDK1 overexpression or hyperactivity and worse prognosis in ovarian, colorectal, and breast cancers." (PMID 29843367, 2018). "Allele and genotype frequencies of the selected tSNPs in CCNB1 and CDK1 and the association with risk of breast cancer." (PMID 24386390, 2013). "Association analysis of the selected tSNPs, diplotypes in CDK1 in relation to event-free survival of breast cancer patients (n=1005)." (PMID 24386390, 2013). "Combined CDK1/2 depletion caused cell cycle arrest and cell death in both anti-estrogen-sensitive and resistant breast cancer cell lines tested." (PMID 20010939, 2010).
breast cancer (continued). "CDK1 is an important member of CDKs involved in controlling events such as DNA replication, mRNA transcription and translation, DNA repair, and cellular morphogenesis, and is closely associated with breast cancer development." (PMID 40000619, 2025). "Hyperactivation of CDK1 is associated with poor prognosis for patients with lung adenocarcinoma, ovarian cancer, renal cell carcinoma, and breast cancer." (PMID 28434945, 2017). "High CDK1 activity has been associated to poor prognosis in breast cancer patients." (PMID 28717182, 2017). "In this study, we hypothesized that the genetic variation in CCNB1 and CDK1 had great impact on susceptibility, progression and survival of breast cancer." (PMID 24386390, 2013). "Stratified analyses between rs2448343 of CDK1 and breast cancer risk by BMI status." (PMID 24386390, 2013). "Risk of breast cancer associated with the combination of 2 susceptible tSNPs in CDK1." (PMID 24386390, 2013). "As haplotype and diplotype analysis may provide more power to detect association than single marker analyses alone, we also detected the associations of haplotypes and diplotypes in CCNB1 and CDK1 with breast cancer risk." (PMID 24386390, 2013). "In addition, exploring pharmacological inhibitors targeting CDK1 or its associated pathways could provide novel therapeutic strategies, particularly for patients with triple-negative or Basal-like breast cancer." (PMID 41278293, 2025). "For example, RNMT (RNA guanine-7 methyltransferase) demonstrated an association with CDK1-cyclin B1 to sync mRNA G1 phase transcription and impact mRNA surveillance and it has also been found to potentially correlate with immune cell infiltration in breast cancer (BC)." (PMID 38735973, 2024). "CDK1 plays an important role in mammalian cell cycles by regulating the G2/M phase transition of eukaryotic mitosis, and its abnormal expression has been reported to be associated with the proliferation and survival of breast cancer and epithelial ovarian cancer." (PMID 34437425, 2021). "After establishing that combined CDK2 and CDK1 depletion caused cell cycle arrest and cell death in both anti-estrogen-sensitive and resistant breast cancer cells, we investigated whether similar effects could be achieved by reducing CDK activity with small-molecule inhibitors." (PMID 20010939, 2010). "In conclusion, the lncRNA CD2BP2‐DT is identified as a crucial driver of breast cancer cell proliferation through the YBX1/CDK1 axis, highlighting its potential as a promising biomarker and therapeutic target for breast cancer." (PMID 39976088, 2025). "NFIX exhibits decreased expression in breast cancer cells, and it impedes breast cancer progression by targeting CDK1 and triggering a G2/M cell cycle arrest." (PMID 40000619, 2025). "Our analysis revealed that CDK1 gene was significantly upregulated, suggesting its potential role in breast cancer pathogenesis." (PMID 41142571, 2025). "Next, we investigated the role of the CD2BP2‐DT/CDK1 regulatory axis in promoting breast cancer proliferation." (PMID 39976088, 2025). "Taken together, our results indicate that CDK1 acts as a multifaceted oncogene in breast cancer, contributing to tumor progression through both cell-intrinsic and immune-related mechanisms." (PMID 41278293, 2025). "Studies have reported that abnormal expression and activity changes of CDK1 can promote tumorigenesis and immune escape of breast cancer through a variety of mechanisms." (PMID 41142571, 2025). "Together, these findings indicate that CDK1 promotes breast cancer cell proliferation primarily by sustaining AKT activation and maintaining the expression of key cell cycle regulators." (PMID 41278293, 2025). "This study enhances breast cancer research by revealing Episesamin's ability to specifically target and downregulate key cell cycle genes CDK1, CDC25A, and PLK1." (PMID 40081286, 2025).